SDC2 (syndecan 2)
Description:
Cell surface proteoglycan which regulates dendritic arbor morphogenesis.
Synonyms: SYND2; HSPG; CD362; HSPG1; fibroglycan
Tractability: Antibody: its Gene Ontology location is reachable by antibodies, with high confidence; UniProt predicts a signal peptide or a membrane-spanning region; the Human Protein Atlas places it where antibodies can reach. PROTAC: ubiquitination databases record sites on it; its protein half-life has been measured; a small molecule that binds it is known.
Gene: Protein-coding gene on chromosome 8 (96,493,410 to 96,611,790, forward strand). Ensembl gene ENSG00000169439.
Subcellular location: Membrane
Subcellular location (Human Protein Atlas): Plasma membrane
Pathways (Reactome):
Disease: Attachment and Entry; Defective B3GALT6 causes EDSP2 and SEMDJL1; Defective B3GAT3 causes JDSSDHD; Defective B4GALT7 causes EDS, progeroid type; Defective EXT1 causes exostoses 1, TRPS2 and CHDS; Defective EXT2 causes exostoses 2; Dengue Virus Attachment and Entry; Dengue Virus-Host Interactions; RSV-host interactions; Respiratory syncytial virus (RSV) attachment and entry
Hemostasis: Cell surface interactions at the vascular wall; Initiation of coagulation cascade; Regulation of clotting cascade
Metabolism: Glycosaminoglycan-protein linkage region biosynthesis; HS-GAG biosynthesis; HS-GAG degradation
Metabolism of proteins: Post-translational protein phosphorylation; Regulation of Insulin-like Growth Factor (IGF) transport and uptake by Insulin-like Growth Factor Binding Proteins (IGFBPs)
Developmental Biology: EPHB-mediated forward signaling
Extracellular matrix organization: Syndecan interactions
Sensory Perception: Retinoid metabolism and transport
Gene Ontology:
Molecular function: identical protein binding; PDZ domain binding; protein binding
Biological process: dendrite morphogenesis; regulation of dendrite morphogenesis; regulation of synapse assembly
Cellular component: extracellular matrix; plasma membrane; cell surface; endoplasmic reticulum lumen; Golgi lumen; lysosomal lumen; membrane
Genetic constraint (gnomAD): Loss-of-function variants: 11 observed, 15.6 expected, observed/expected ratio (o/e) 0.71, 90% interval 0.44 to 1.17. The upper end of that interval is the gene's LOEUF score, 1.17, which puts it in group 5 of 6, group 1 being the genes least tolerant of losing a copy. Missense variants: 185 observed, 198.98 expected, observed/expected ratio (o/e) 0.93, 90% interval 0.82 to 1.05. Synonymous variants: 73 observed, 73.95 expected, observed/expected ratio (o/e) 0.99, 90% interval 0.82 to 1.2.
Homologues: Orthologues: chimpanzee SDC2 (99% identical), macaque SDC2 (98% identical), pig SDC2 (96% identical), guinea pig SDC2 (90% identical), mouse Sdc2 (84% identical), rat Sdc2 (75% identical), tropical clawed frog sdc2 (55% identical), zebrafish sdc2 (53% identical), Drosophila melanogaster Sdc (26% identical), Caenorhabditis elegans sdn-1 (19% identical). Paralogues in human: SDC3 (36% identical), SDC4 (35% identical), SDC1 (32% identical).
Diseases named in the same sentence as SDC2 in open-access papers:
SDC2 is named in the same sentence as 121 diseases in open-access papers, as found by Europe PMC text mining. Sharing a sentence is not in itself a finding about the gene and the disease. The quoted sentences say what the papers report.
colorectal cancer (39 papers, 2013 to 2026). A primary or metastatic malignant neoplasm that affects the colon or rectum. "In recent years, SDC2 has emerged as a promising methylation site, with various studies indicating that SDC2 possesses good diagnostic performance for colorectal cancer." (PMID 39717169, 2024). "Methylated SDC2 has been proved as a diagnostic marker for human colorectal cancer (CRC), noninvasive stool DNA-based methylation testing also emerges as a novel approach for detecting CRC." (PMID 35436855, 2022). "Some studies on methylated Syndecan 2 (SDC2) have shown that it has a great diagnostic ability in colorectal cancer." (PMID 35754025, 2022). "Our subgroup analysis also showed that whether ACTB was used as a reference also affected the diagnostic efficacy of SDC2 methylation for colorectal cancer." (PMID 35754025, 2022). "The aim of this study was to probe the methylation status of SEPT9, BMP3, NDRG4, and SDC2 in stool and study whether methylation of these genes is associated with colorectal cancer." (PMID 31602277, 2019). "A recent study showed that co-upregulation of CASK and syndecan-2 in colorectal cancer is associated with an unfavorable prognosis, suggesting that CASK could be a prognostic factor for colorectal cancer metastasis." (PMID 26869927, 2016). "Fecal DNA methylation of the syndecan-2 (SDC2) gene is being explored as a noninvasive biomarker for colorectal cancer (CRC) detection." (PMID 41589081, 2026). "In colorectal cancer, SDC2 overexpression is strongly correlated with LNM, cancer stage, vascular invasion, and distant metastasis." (PMID 40940401, 2025). "In colorectal cancer, higher expression of syndecan-2 is described, as well as in lung adenocarcinoma and pancreatic tumors, where syndecan-3 is also elevated." (PMID 38727261, 2024). "This meta-analysis aimed to evaluate the comparative diagnostic efficacy of Syndecan-2(SDC2) and Septin-9(SEPT9) in the early detection of colorectal cancer (CRC)." (PMID 39717169, 2024). "The quantitative methylation-specific PCR technique was used to detect faecal methylated syndecan-2 (mSDC2) in patients who received the screening of colorectal cancer (CRC)." (PMID 37783044, 2023). "Our analysis showed that the combined sensitivity and specificity of SDC2 methylation for colorectal cancer diagnosis was 0.81 and 0.95, respectively." (PMID 35754025, 2022). "Here, we developed the ColoCaller test, which simultaneously detects the methylation status of the SDC2, TFPI2, WIF1, and NDRG4 genes in stool DNA, to optimize the screening of gastric and colorectal cancer in high-risk populations." (PMID 35419280, 2022). "The expression of SDC2 is upregulated by demethylation and inhibition of histone deacetylation in colorectal cancer cells with SDC2 methylation." (PMID 35055034, 2022). "The SDC2 promotor region is frequently hipermethylated in colorectal cancer and has been detected in blood and stool samples from colorectal cancer patients." (PMID 35055034, 2022). "Some DNA methylation biomarkers such as Septin9 (SEPT9), Secreted frizzled- related protein 2 (SFRP2), and Syndecan 2 (SDC2) from blood or stool have been considered as feasible biomarkers for early detection of colorectal cancer." (PMID 35754025, 2022). "Two independent researchers conducted a comprehensive literature search to identify all relevant studies on SDC2 methylation for the diagnosis of colorectal cancer from inception to March 1, 2021." (PMID 35754025, 2022). "SDC2, on the other hand, is another biomarker found to be hypermethylated in most colorectal cancer patients." (PMID 35754025, 2022). "Our study was the first meta-analysis to investigate the performance of SDC2 methylation for colorectal cancer screening." (PMID 35754025, 2022). "The study in which we found a detailed population description showed the higher sensitivity of SDC2 methylation for colorectal cancer diagnosis." (PMID 35754025, 2022).
colorectal cancer (continued). "Recently, hypermethylation of SDC2 has also been found in the feces or blood samples of most colorectal cancer patients, indicating its potential as a non-invasive molecular diagnostic biomarker for early detection." (PMID 35754025, 2022). "Overexpression of syndecan-2 (SDC2) in HT29 colorectal cancer cells activates PKCγ and the FAK/ERK signaling pathway that induces the expression of MMP-7 involved in the shedding of E-cadherin." (PMID 36358747, 2022). "Although evaluation of SDC2 methylation is indicated for early detection of colorectal cancer, it seems that assay sensitivity is superior for stage III/IV, while for stage I/II is satisfactory, thus displaying a limited stage specificity." (PMID 34638449, 2021). "Syndecan-2 gene methylation was reported as a frequent event in precancerous lesions and appears detectable in bowel lavage fluid to identify patients with colorectal cancer." (PMID 32351878, 2020). "Relatively speaking, SDC2 has been well studied in various tumors, especially in colorectal cancer, lung cancer, prostate cancer, and esophageal squamous cell carcinoma." (PMID 33178362, 2020). "New biomarkers such as syndecan-2 gene methylation (with improved detection sensitivity and specificity at lower costs) should lead to a great improvement in colorectal cancer screening." (PMID 32351878, 2020). "The ColoDefense assay was used to quantify methylation levels of SEPT9 and SDC2 genes in 19 colorectal cancer tissues and paired adjacent paracancer tissues." (PMID 31089394, 2019). "In colorectal cancer, the cell surface proteoglycan syndecan-2 is upregulated and increases cell migration." (PMID 30027065, 2018). "In highly metastatic colorectal cancer cells, syndecan-2 expression is enhanced by fibronectin secreted by stromal cells." (PMID 26869927, 2016). "In several colorectal cancer cell lines, syndecan-2 is highly expressed compared to normal cell lines." (PMID 23705906, 2013). "Overall, our results show that stromal ECM induces the expression and synthesis of syndecan-2 in HCT-116 colorectal cancer cells and that the fibronectin component of ECM is mainly responsible for this effect." (PMID 23705906, 2013). "Syndecan-2 has been found to be highly expressed in colorectal cancer cell lines and appears to be critical for cancer cell behavior." (PMID 23705906, 2013). "Increased syndecan-2 expression has been reported in several colorectal cancer cell lines with a concomitant decrease in syndecans-1 and -4." (PMID 23705906, 2013). "Our results showed that fibronectin is mainly responsible for the increased expression and synthesis of syndecan-2 in HCT-116 colorectal cancer cells that was induced by stromal fibroblast ECM." (PMID 23705906, 2013). "This study showed that syndecan-2 mRNA expression in a highly metastatic colorectal cancer cell line, HCT-116, is enhanced when the cancer cells were cultured in the presence of ECM that was produced by fibroblasts." (PMID 23705906, 2013). "Single-cell RNA sequencing (scRNA-seq) analysis from colorectal cancer patients showed that SPP1+ TAMs expressing syndecan-2 (SDC2) were more likely to interact with CAFs expressing MMP-2 through the combination of SDC2 and MMP-2 to promote the activation of CAFs and tumor tissue fibrosis." (PMID 35898884, 2022). "The results showed that populations from different countries might be the source of heterogeneity, and that SDC2 methylation had poorer screening efficacy for colorectal cancer in populations derived from China than in other countries." (PMID 35754025, 2022). "Our analysis revealed that methylated SDC2 could be considered as a potential novel biomarker to screen for colorectal cancer." (PMID 35754025, 2022).
colorectal cancer (continued). "Although previous meta-analyses and systematic reviews have analyzed and evaluated SDC2 methylation derived from feces and blood, respectively, for colorectal cancer screening, they included a small number of articles and lacked specific study analysis of SDC2 methylation." (PMID 35754025, 2022). "Similarly, multi-target stool DNA tests involving methylation detection of NDRG4 in combination with BMP3 or SDC2 in the diagnosis of colorectal cancer have the sensitivities ranging from 85%-98% and specificity ranging from 86.6%-90% 32, 46-50." (PMID 33391430, 2021). "The DNA methylation biomarkers BMP3 (bone morphogenetic protein 3), NDRG4 (N-myc downstream-regulated gene 4) and SDC2 (syndecan-2) has been extensively studied and are served as an alternative method in screening colorectal cancers and neoplasms 5, 16, 31, 35-44." (PMID 33391430, 2021). "Moreover, integration of SEPT9, NDRG4, and SDC2 methylation demonstrated high feasibility for detecting colorectal cancer and adenoma, with better performance on colorectal cancer than adenoma." (PMID 31602277, 2019). "Levels of glypican-1 and syndecan-2 are also increased in colorectal cancer." (PMID 31620357, 2019). "Previously, we reported that we identified that CpG sites of SDC2 were aberrantly methylated in tumor tissues of most CRC patients through comprehensive methylation analysis and demonstrated a high potential of quantification of SDC2 methylation in blood for early detection of colorectal cancer." (PMID 29225717, 2017). "This is consistent with previous studies showing that syndecan-2 expression in colorectal cancer-derived HT-29 M6 epithelial cells induces a migratory phenotype that is associated with noticeable increases in cell proliferation, invasion and anchorage-independent growth." (PMID 23705906, 2013). "The pooled results of our meta-analysis have confirmed the difference in the SDC2 methylation between patients with tumors of colorectal and healthy individuals, which sheds light on SDC2 methylation as a promising novel screening biomarker for early detection of colorectal cancer." (PMID 35754025, 2022). "Colorectal cancer diagnostic assays of methylated sequences of either the SEPT9 or VIM genes are now commercially available for detection in plasma and stool samples respectively and other genes such as THBSI and SDC2 are also being evaluated for plasma-based diagnosis." (PMID 24485021, 2014). "As a non-invasive detection method, the dual detection of SDC2/TFPI2 will be an easy and precise screening tool for colorectal cancer and its precancerous lesions." (PMID 35004840, 2021). "Our results showed that in a highly metastatic colorectal cancer cell line, HCT-116, syndecan-2 expression is enhanced by fibroblast ECM, while the expression of other syndecans decreased." (PMID 23705906, 2013). "In summary, the cell surface heparan sulfate proteoglycan adhesion receptor, syndecan-2, plays a critical role in regulating the tumorigenic activity of HCT-116 colorectal cancer cells." (PMID 23705906, 2013). "The overexpression of SDC2 in colorectal cancer results in induction of EMT and the upregulation of N-cadherin, Slug, Twist, vimentin, and MAPK signaling pathway activation, while SDC2 knockdown reduces cancer cell proliferation, migration, and invasion, and induces cell apoptosis." (PMID 36358747, 2022). "Methylated SDC2 and TFPI2 are widely used for colorectal cancer (CRC) detection." (PMID 35227195, 2022).
colon carcinoma (35 papers, 2008 to 2024). "Further studies are needed to clarify the mechanism underlying the SDC2-prompted activating cleavage of pro-MMP-7 at the colon cancer cell surface." (PMID 35682569, 2022). "In colon cancer, SDC2 was significantly associated with tumor growth, cell migration, tumor stage, lymph and distant metastasis, and vascular invasion." (PMID 35127947, 2022). "Therefore, this dynamic interaction, including syndecan-2, fibronectin, and integrin, might be a possible mechanism underlying the metastatic characteristics of colon cancer cells." (PMID 30027065, 2018). "Through this regulation, increased SDC2 promotes the cell adhesion and spreading of colon cancer cells." (PMID 35682569, 2022). "SDC2 was highly expressed in colon cancer, breast cancer, and glioma tissues while generally not expressed in matched normal tissues." (PMID 35127947, 2022). "For example, PKCγ interacts with fascin and Rac at the edge of cells to promote the migration of colon cancer cells, and the syndecan-2 cytoplasmic domain regulates matrix metalloproteinase-7 expression through PKC-mediated activation of FAK/ERK signaling." (PMID 35625898, 2022). "Elevated expression levels of syndecan-1 have been reported in breast cancer, pancreatic cancer, and squamous cell carcinoma of the lung, whereas increased levels of syndecan-2 have been observed in melanoma and colon cancer." (PMID 35128576, 2022). "For example, matrix metalloproteinase-7 (MMP-7) binds to the extracellular domain of SDC2 and subsequently undergoes activation in colon cancer cells." (PMID 35682569, 2022). "EarlyTectTM-Colon Cancer test exhibited high analytical sensitivity and specificity for SDC2 methylation detection, as well as high reproducibility." (PMID 33858326, 2021). "Because the extracellular domain of syndecan-2 is cleaved by MMP-7 in colon cancer cells, it is likely that MMP-7 is involved in syndecan-2 shedding when BFT contacts IECs." (PMID 34769248, 2021). "Syndecan 2 (Sdc-2) expression is increased in a range of cancers including lung adenocarcinoma and colon cancer, where it promotes expression of matrix metalo-proteinase 9 and 7 (MMP9 and MMP7) respectively." (PMID 33330449, 2020). "Although some previous studies using colon carcinoma cells have described alterations in the transcriptions of syndecan-2 and -4, our previous work on RSCRCs was only able to detect overexpression of syndecan-1 in metastatic tumors." (PMID 29940912, 2018). "The addition of purified recombinant extracellular domain of syndecan-2 to the cell medium completely blocked the adhesion of colon cancer cells on the ECM." (PMID 30027065, 2018). "For example, SDC2 has been shown to be overexpressed in colon cancer cell lines and inhibition of SDC2 in these cells results in cell cycle arrest." (PMID 30197623, 2018). "One study reported that syndecan-2 regulates colon carcinoma cell migration through Tiam1-dependent Rac activation." (PMID 26869927, 2016). "We previously reported that elevated expression of syndecan-2 potentiates the tumorigenic activity of colon carcinoma cells but the exact molecular regulatory mechanism underlying this effect was not known." (PMID 25686828, 2015). "Recent data also suggests that syndecan-2, normally considered a mesenchymal proteoglycan, is upregulated and a potential target in colon carcinoma." (PMID 25623282, 2015). "Since shed syndecan-2 was found to enhance the anchorage-independent growth of colon cancer cells, we believe that the role of shed sydecan-2 is not limited to autocrine signaling." (PMID 25686828, 2015). "Because earlier studies showed the cell surface heparan sulfate proteoglycan, syndecan-2, sheds from colon cancer cells in culture, the functional roles of shed syndecan-2 were assessed." (PMID 25686828, 2015).